CMA1 (chymase 1)
Description:
Major secreted protease of mast cells with suspected roles in vasoactive peptide generation, extracellular matrix degradation, and regulation of gland secretion.
Synonyms: CYH; MCT1; chymase
Tractability: Small molecule: a drug acting on it is in phase 2 or 3 trials; a structure with a bound ligand is known; a high-quality ligand is known; it belongs to a druggable protein family. Antibody: its Gene Ontology location is reachable by antibodies, with high confidence; UniProt places it where antibodies can reach, with medium confidence; UniProt predicts a signal peptide or a membrane-spanning region. PROTAC: a small molecule that binds it is known.
Target class: Serine protease; Enzyme; Serine protease PA clan; Serine protease S1A subfamily; Protease
Chemical probes: BI-1942 (high quality)
Gene: Protein-coding gene on chromosome 14 (24,505,353 to 24,508,265, reverse strand). Ensembl gene ENSG00000092009.
Subcellular location: Secreted; Cytoplasmic granule
Subcellular location (Human Protein Atlas): Cytoplasmic bodies; Cytosol; Predicted to be secreted
Pathways (Reactome):
Extracellular matrix organization: Activation of Matrix Metalloproteinases
Metabolism of proteins: Metabolism of Angiotensinogen to Angiotensins
Signal Transduction: Signaling by SCF-KIT
Gene Ontology:
Molecular function: endopeptidase activity; serine-type endopeptidase activity; serine-type peptidase activity; peptide binding
Biological process: basement membrane disassembly; cytokine precursor processing; extracellular matrix disassembly; regulation of inflammatory response; angiotensin maturation; protein maturation; cellular response to glucose stimulus; midbrain development; peptide metabolic process; positive regulation of angiogenesis; protein catabolic process; protein processing; proteolysis
Cellular component: cytoplasmic ribonucleoprotein granule; extracellular matrix; extracellular region; secretory granule
Genetic constraint (gnomAD): Loss-of-function variants: 27 observed, 23.56 expected, observed/expected ratio (o/e) 1.15, 90% interval 0.84 to 1.58. The upper end of that interval is the gene's LOEUF score, 1.58, which puts it in group 6 of 6, group 1 being the genes least tolerant of losing a copy. Missense variants: 421 observed, 320.46 expected, observed/expected ratio (o/e) 1.31, 90% interval 1.21 to 1.42. Synonymous variants: 152 observed, 124.99 expected, observed/expected ratio (o/e) 1.22, 90% interval 1.07 to 1.39.
Homologues: Orthologues: chimpanzee CMA1 (98% identical), macaque CMA1 (81% identical), guinea pig CMA1 (78% identical), mouse Cma1 (74% identical), rat Cma1 (72% identical), dog CMA1 (68% identical), rabbit CMA1 (62% identical), tropical clawed frog ctsg (42% identical). Paralogues in human: GZMB (53% identical), CTSG (52% identical), GZMH (49% identical), KLK13 (37% identical), KLK6 (33% identical), AZU1 (32% identical).
Diseases named in the same sentence as CMA1 in open-access papers:
CMA1 is named in the same sentence as 31 diseases in open-access papers, as found by Europe PMC text mining. Sharing a sentence is not in itself a finding about the gene and the disease. The quoted sentences say what the papers report.
asthma (3 papers, 2019 to 2025). "Chymase 1 (CMA1) gene is located on the long arm of chromosome 14, and polymorphisms in CMA1 have been reported to be associated with asthma, heart failure, and even aortic stenosis." (PMID 31888494, 2019). "We then observed that the pediatric asthma subjects in high temperature exposure showed increased Tiam2 and Cma1 expression." (PMID 40313552, 2025). "Extreme temperature decreased Wfdc21, Cttnbp2, Cib3, and Cma1 expression in mild and moderate asthma, while increased expression in severe asthma patients." (PMID 40313552, 2025). "We observed that the pediatric asthma subjects in the extreme high temperature group exhibited higher expression of Tiam2 and Cma1, whereas Wfdc21, Cib3, and Sftpc expression were decreased." (PMID 40313552, 2025). "The significant findings of this work indicate that extreme high temperature increased Cma1 and Tiam2 expression, and extreme low temperature increased Sftpc and Nxnl expression in asthma, especially among pediatric populations." (PMID 40313552, 2025). "Extreme low temperature decreased Wfdc21, Cttnbp2, Cib3, and Cma1 expression in mild and moderate asthma, while increased expression in severe asthma." (PMID 40313552, 2025). "We observed that extreme low temperature decreased Wfdc21, Cttnbp2, Cib3, and Cma1 expression in mild and moderate asthma, while increased expression in severe asthma." (PMID 40313552, 2025). "Pediatric asthma subjects in the extreme low temperature group showed decreased expression of Wfdc21, Cib3, Cma1, and Dld, while Sftpc and Nxnl expression increased." (PMID 40313552, 2025). "In addition, asthma subjects in the extreme temperature fluctuation group showed decreased expression of Wfdc21, Cib3, Gpr171, and Cttnbp2, while Tiam2 and Cma1 expression increased." (PMID 40313552, 2025). "Adult asthma subjects in the extreme temperature fluctuation group showed consistently decreased Wfdc21, Cib3, Gpr171, and Cttnbp2 expression, while increased Tiam2 and Cma1 expression." (PMID 40313552, 2025). "Cib3, and Cma1 were significantly upregulated in severe asthma patients." (PMID 40313552, 2025).
aortic stenosis (2 papers, 2014 to 2019). Aortic valve stenosis is a aortic valve disease caused by the incomplete opening of the aortic valve. "Common genetic variants and haplotypes at the promoter of the CMA1 gene are associated with LVH in male patients with aortic stenosis." (PMID 24823657, 2014). "The goal of this study was to examine the association between genetic variations in the CMA1 locus and LVH using a comprehensive tagging polymorphism and haplotype approach in a large cohort of patients with aortic stenosis." (PMID 24823657, 2014). "We investigated the association between polymorphisms and haplotypes of the chymase 1 gene (CMA1) and the left ventricular mass index (LVM/BSA) in a large cohort of patients with aortic stenosis (AS)." (PMID 24823657, 2014).
atrial fibrillation (2 papers, 2019 to 2022). A disorder characterized by an electrocardiographic finding of a supraventricular arrhythmia characterized by the replacement of consistent P waves by rapid oscillations or fibrillatory waves that vary in size, shape and timing and are accompanied by an irregular ventricular response. "This study aimed to examine the association between chymase 1 gene (CMA1) polymorphisms and atrial fibrillation (AF) in a Chinese Han population." (PMID 31888494, 2019).
emphysema (2 papers, 2022 to 2025). "In tobacco-related COPD (COPD-T), several studies have reported mast-cell activation with chymase-1 release, an event that could favor inflammation, macrophage influx, and airway remodeling or emphysema." (PMID 40722673, 2025). "The latest study also found that mast cells stimulate macrophages to release TNF-α by secreting chymase-1 in COPD, which further reflects the active interaction of immune cells in emphysema." (PMID 36248880, 2022).
Hypertension (2 papers, 2013 to 2021). The presence of chronic increased pressure in the systemic arterial system. "These genes, Cma1 and Ctsg, are therefore compelling hypertension candidate genes, particularly as the histidine at codon 94 in Cma1 that is uniquely variant in FHH among all rat strains is conserved in all mammals." (PMID 23890820, 2013). "In humans, a haplotype at CMA1 has been weakly associated (p = 2 × 10−4) with hypertension in Han Chinese, and in mice, chymase 1 has been proposed to modulate regulation of blood pressure by angiotensin II." (PMID 23890820, 2013).
rosacea (2 papers, 2020 to 2023). A chronic erythematous skin disorder that affects the face. "Moreover, EGCG also reduced the expressions of the neutrophil-attracting chemokines (Cxcl15 and Cxcl1), macrophage markers (Cd68 and Itgam), and mast cell-related genes (Tpsab1 and Cma1) in LL-37-induced rosacea-like lesions." (PMID 36937834, 2023).
atopic dermatitis (1 paper, 2025). "It is worth mentioning that Cma1 is stored in the granules of mast cells, and atopic dermatitis is closely related to mast cell activation." (PMID 40362388, 2025).
basal cell carcinoma (1 paper, 2025). A carcinoma involving the basal cells. "Additionally, a decrease in the expression of tryptase (TPSAB1) and chymase (CMA1) genes has been reported in MC compared to normal skin and basal cell carcinoma." (PMID 41373472, 2025).
cardiac hypertrophy (1 paper, 2014). "The polymorphisms and haplotypes of the CMA1 locus are associated with cardiac hypertrophy in male patients with symptomatic AS." (PMID 24823657, 2014).
COVID-19 (1 paper, 2022). A disease caused by infection with severe acute respiratory syndrome coronavirus 2. "The levels of the proteases in four patients subsequently deceased from COVID-19 were comparable to the levels in the patients with severe COVID-19: CPA3 (21.54 ±6.6 vs. 22.25 ±5.7 ng/ml, p = 0.72); CMA1 (2426 ±1113 vs. 2387 ±720 ng/ml, p = 0.73) and for TPSB2 (27.5 ±17 vs. 30.04 ±17 ng/ml, p=0.95)." (PMID 36225927, 2022).
depression (1 paper, 2026). "Consistently, the mRNA levels of mast cell‐specific proteases, such as Chymase 1 (CMA1), Carboxypeptidase A 3 (CPA3), and Tryptase Beta 2 (TPSB2) were also upregulated in the brain from depression model mice." (PMID 41556446, 2026). "Similarly, the mast cell‐specific proteases (CMA1, CPA3, and TPSB2) that were increased in depression model mice were down‐regulated by DSCG treatment as well." (PMID 41556446, 2026).
gastric cancer (1 paper, 2021). A primary or metastatic malignant neoplasm involving the stomach. "The level of CMA1, a key gene, is significantly correlated with gastric cancer prognosis and infiltration level." (PMID 34827136, 2021).
glioma (1 paper, 2020). A benign or malignant brain and spinal cord tumor that arises from glial cells (astrocytes, oligodendrocytes, ependymal cells). "Faint expression of CMA1 was evident in glioma where CMA1-positive cells co-localized with TAMRA-FP hotspots, whereas CMA1-positive cells were scarce in TAMRA-FP hotspot clusters." (PMID 32190011, 2020).
Granuloma (1 paper, 2025). A compact, organized collection of mature mononuclear phagocytes, which may be but is not necessarily accompanied by accessory features such as necrosis. "Importantly, when restricting analysis to CMA1+ cells, the dual-positive CMA1+LOC102140229+ MC subset was proportionally more abundant in less severe, 10-week granulomas (OR = 0.51, p < 1×10−9)." (PMID 39314389, 2025).
mastocytoma (1 paper, 2014). A localized tumor composed of sheets of mast cells without atypia. "Furthermore, enforced miR-9 expression in murine mastocytoma cell lines and normal murine BMMCs with low basal levels of miR-9 enhanced invasion and induced the expression of several target genes associated with metastasis, including chymase (CMA1) and heparinase (HSPE)." (PMID 24517413, 2014).
Obesity (1 paper, 2020). Accumulation of substantial excess body fat. "In the independent validation, cohort 1 of n = 32 patients with obesity whose VAT gene expression was assessed by microarrays, all MC genes probe sets (KIT, TPSB2, CMA1) exhibited significant negative correlations with macrophage gene probes (CD68, Mac2, IGTAX(CD11c))." (PMID 32575785, 2020). "Contrary to our hypothesis, patients with obesity and low VAT-MC gene expression (below median expression of both TPSB2 and CMA1) were either not significantly different, or in some parameters trended to, or exhibited significantly worse clinical parameters." (PMID 32575785, 2020).
psoriasis (1 paper, 2021). An autoimmune condition characterized by red, well-delineated plaques with silvery scales that are usually on the extensor surfaces and scalp. "As a result, we found that the mRNA expression level of KIT, ENPP3, CMA1, CTSG, TPSAB1 and TPSG1 is decreased in PP compared with PN and NN, indicating the fraction of total mast cells is decreased in psoriasis." (PMID 34887864, 2021).
viral infection (1 paper, 2022). "TPSB2 and CMA-1 have been demonstrated to induce vascular leakage in response to viral infection, which may explain the increased lung damage observed in CT scans." (PMID 36225927, 2022).
tumor (8 papers, 2017 to 2025). "Aside from the loss of epithelial cell polarity and EMT, mast cell activation in tumor areas was identified by an in silico predicted CMA1 activity on the bile peptide markers as CCA-associated event." (PMID 31900160, 2020). "CCR4, CMA1, ADCY1, RDH12, and ENTPD2 exhibited higher expression levels in the low-risk group, indicating their possible tumor-suppressive functions." (PMID 40243888, 2025). "Third, tumor subsets enriched for immune markers, including cytotoxic immune genes (e.g., Prf1, Gzmb, Gzmg) and mast cell protease genes (e.g., Mcpt1, Cma1, Tpsb2)." (PMID 40171265, 2025). "In the tumor tissue, CMA1 mRNA was low throughout, while MRC1 mRNA levels showed high inter-individual variations." (PMID 29176937, 2017). "On the other hand, we found that the chymotryptic serine proteinase Cma1, the endogenous opioid polypeptide hormone Penk, Guanine nucleotide-binding protein Gnai1 and the chemokine receptor Ccr3 were among the most down-regulated genes in SSMs after the influence of a local tumor mass." (PMID 34168645, 2021). "For the mast cell marker CMA1 and the macrophage marker MRC1, mRNA-levels in the normal mucosa of CRC patients were elevated compared to both healthy and tumor tissue." (PMID 29176937, 2017). "Conversely, low-risk patients demonstrated higher expression of metabolic genes, such as CMA1 and ADCY1, which may enhance metabolic homeostasis and anti-tumor immunity." (PMID 40243888, 2025). "In addition, CMA1 and MRC1 were upregulated in patient normal mucosa compared to both healthy and tumor tissue." (PMID 29176937, 2017).
cancer (6 papers, 2020 to 2025). A tumor composed of atypical neoplastic, often pleomorphic cells that invade other tissues. "Microarray analysis of cancer tissues from AOM/DSS and AOM/DSS/Ab mice revealed profound differences in the expression of genes associated with mast cells, namely Mctp1, Mctp2, Mctp4, Cma1, Fcer1a, Pla2g2e, and Cpa3." (PMID 37185713, 2023). "Microarray analyses and RT-qPCR revealed that mast cell protease 1, mast cell protease 2, and chymase 1 were up-regulated in cancer tissue of AOM/DSS mice; however, those mast cell related genes were downregulated in cancer tissue of AOM/DSS mice with infliximab." (PMID 37185713, 2023).
CMA1 also shares sentences with these, for which no sentence is quoted: infection (2 papers); pterygium (2); anaphylaxis (1); autoimmune disease (1); breast carcinoma (1); chronic kidney disease (1); heart disease (1); heart failure (1); ischemia (1); neurological disorders (1); prostate carcinoma (1).